XBP1 (X-box binding protein 1)
Diseases named in the same sentence as XBP1 in open-access papers (continued):
Sharing a sentence is not in itself a finding about the gene and the disease.
Obesity (51 papers, 2013 to 2026). Accumulation of substantial excess body fat. "Our study supports that maternal obesity-induced specific activation of IRE1α-XBP1 plays a critical role in placental pathophysiology associated with obesity." (PMID 36819099, 2023). "XBP1 deficiency prevented obesity in mice fed a high fat diet but XBP1 deficient mice developed insulin resistance." (PMID 26157705, 2015). "Interestingly, mice with a conditional deletion of Xbp-1 in neurons and glia are more susceptible to diet-induced obesity and become leptin-resistant." (PMID 38500817, 2024). "In addition, the increased iNOS-induced metaflammation is associated with impaired XBP1 processing in obesity." (PMID 35011092, 2022). "Xbp1 deletion may therefore result in impaired compensatory insulin secretion under conditions of obesity, causing diabetes." (PMID 35316840, 2022). "This defective IRE1α-mediated XBP1 splicing process has been proved in the liver in conditions of both genetic and diet-induced obesity; and these ER-remodeling-associated interactions are worth further examination in adipocytes in the obesity setting." (PMID 33795017, 2021). "XBP1 is an oestrogen-responsive gene, however it is also activated in response to endoplasmic reticulum (ER) stress which is caused by numerous factors, including obesity." (PMID 32069845, 2020). "Furthermore, obesity-mediated iNOS and nitric oxide cause insulin resistance by s-nitrosylating the IRE1α, which affects the ER homeostasis role by inhibiting the XBP1 splicing, but maintaining the IRE1α phosphorylation and c-Jun N-terminal kinase (JNK) activation and its mediated inflammation." (PMID 32397116, 2020). "A recent study showed that the upregulation of spliced X-box binding protein 1 (Xbp1s) in AGRP neurons reverses diet-induced obesity and improves leptin and insulin resistance." (PMID 40531768, 2025). "Overexpression of Xbp-1s enhanced TFEB transcription and autophagy, while overexpression of Tfeb ameliorated the glucose intolerance seen in Xbp1 liver knockout mice with diet-induced obesity." (PMID 38500817, 2024). "Our study sheds light on the link between XBP1 hyperactivation and adipogenesis, providing potential insights for designing safe and effective anti-obesity therapeutics for preclinical investigations and clinical applications." (PMID 38167723, 2024). "Here, the authors introduce KT-NE, a nanoemulsion combining KIRA6 (an XBP1 inhibitor) and α-Tocopherol, easing ER and oxidative stress in (pre)adipocytes and showing anti-obesity effectiveness." (PMID 38167723, 2024). "In the individuals with obesity, we found higher abundance of both XBP1 expression and splicing, and the total levels correlated negatively with CKB (rho = −0.5129; P = 0.0027), also after correction for BMI in a multiple regression analysis." (PMID 39675471, 2024). "When ERS occurs in obesity, XBP-1 can up-regulate the expression of response genes, promote the synthesis of TG and lead to the accumulation of TG in the liver." (PMID 37868068, 2023). "Obesity promotes hepatic inositol requiring enzyme 1 α (IRE1α) activation and X-box binding protein 1 (XBP1)-drived production of cholesterol, which in turn elicits immunosuppression by enhancing the functions of MDSCs." (PMID 37266440, 2023). "Insulin levels and the insulin AUC during the OGTT were significantly increased in obese β-Xbp1+/+Ob mice compared with lean β-Xbp1+/+Wt mice, characteristic of the beta cell compensatory response to obesity." (PMID 35316840, 2022). "The expression of insulin and Pc2 was significantly induced in the islets of obese β-Xbp1+/+Ob mice compared with lean β-Xbp1+/+Wt mice, providing evidence of an improved beta cell capacity to meet greater insulin demand in obesity." (PMID 35316840, 2022). "Fed blood glucose levels in obese β-Xbp1−/−Ob mice were significantly increased 1 and 2 weeks after Xbp1 deletion compared with all other groups, demonstrating that Xbp1 deletion leads to diabetes under conditions of obesity." (PMID 35316840, 2022).
Obesity (continued). "Analysis of subcutaneous adipose tissue samples revealed that the mRNA expression levels of ER stress markers (Xbp1, sXbp1, Atf6, Atf4, and Grp78) were significantly higher in the hypertrophic obesity mice than in the control mice." (PMID 36035215, 2022). "Mice with inducible beta cell-specific Xbp1 deletion were studied under normal (chow diet) or metabolic stress (high-fat diet or obesity) conditions." (PMID 35316840, 2022). "The mRNA expression levels of ER stress markers (Xbp1, sXbp1, Atf4, Atf6, and Grp78) were significantly higher in the ASCs treated with hypertrophic obesity adipocyte-derived EVs than in the ASCs treated with control adipocyte-derived EVs." (PMID 36035215, 2022). "XBP1s plays a vital role in metabolic regulation and XBP1 haplodeficiency leads to the development of obesity and type 2 diabetic features." (PMID 32992509, 2020). "Furthermore, CypB’s PPIase activity affects lipid metabolism through key pathways including AKT/mTOR and IRE1α-XBP1, helping to prevent and treat obesity-related metabolic disorders such as diabetes and hyperlipidemia." (PMID 39125345, 2024). "IXA4, the most selective IRE1α-XBP1 activator, can promote the degradation of Alzheimer’s disease-associated amyloid precursor protein (APP) mutants, prevent APP-associated mitochondrial dysfunction, and remodel obesity-induced metabolic dysfunction." (PMID 35765067, 2022). "XBP1s is a master regulator of ER function and protein folding capacity, and a lack of one allele of XBP1 leads to the development of obesity and dysregulation of glucose homeostasis." (PMID 32992509, 2020). "Previous studies have reported a pivotal role of XBP1 in the development of several diseases such as Alzheimer’s Disease, diabetic retinopathy, neurodegeneration, insulin resistance, and obesity." (PMID 31630283, 2020). "MiR-30c-2-3p which targets Xbp1 was specifically upregulated in BAT due to HFD induced obesity." (PMID 29507687, 2018). "Specifically, in the hypothalamic region of the brain, elevated UPR activity has been shown to potentiate diet-induced obesity and mice overexpressing UPR effector X-box binding protein 1 (XBP1) in POMC neurons are resistant to diet-induced obesity via cell- and non–cell-autonomous mechanisms." (PMID 29457782, 2018). "However, contradictory findings suggest that XBP-1, which has glucose-lowering and insulin-sensitizing effect in obesity, induces, in concert with NF-κB, the transcription of genes encoding inflammatory cytokines such as interleukin 1β." (PMID 29847581, 2018). "Additionally, disruption of signalling between p85s and XBP1 occurs in obesity, where p85 serves to activate XBP1 after insulin simulation, resulting in decreased localization of XBP1 to the nucleus for the activation of the UPR." (PMID 24909749, 2014). "Also, further studies to investigate the underlying mechanism for different response of PERK/CHOP and IRE1α/XBP1 pathway to long term high-fat diet would help understanding the pathogenesis of diet-induced obesity." (PMID 24223162, 2013). "Stress during chondrogenic differentiation of obese and morbidly obese donors has not been assessed before, but our data clearly show an increase in both XBP1 and sXBP1 expression, indicating that obesity‐related stress conditions may also affect chondrogenic differentiation of BM‐MSCs." (PMID 40775434, 2025). "In conclusion, our study presents a strategy to alleviate the burden of obesity and reduce the risk of adiposity-related complications (e.g., NAFLD) by an ER stress- and oxidative stress- relieving nano-platform KT-NE to scavenge excessive ROS and restrain XBP1 hyperactivation in adipose tissues." (PMID 38167723, 2024). "Our findings represent the first step in understanding of one of key ER signaling pathway, also referred to IRE1α-XBP1, in placental pathophysiology affected by obesity, which may be an important mechanism accounting for the observed higher maternal and perinatal risks." (PMID 36819099, 2023).
Obesity (continued). "Our findings represent the first step in the understanding of one of the key ER signaling pathways, also referred to IRE1α-XBP1, in placental pathophysiology affected by obesity, which may be an important mechanism accounting for the observed higher maternal and perinatal risks." (PMID 36819099, 2023). "Therefore, if a contribution of the IRE1α-XBP1 pathway to energy consumption in vivo is elucidated, the IRE1α-XBP1 pathway in brown adipocytes may have a potential for treating obesity." (PMID 26568450, 2015). "PTP1B silencing in experimental mice similarly prevented obesity-induced ER stress by inactivating CHOP, BIP, GRP94, ATF4 and XBP1 factors." (PMID 37020593, 2023). "In this study, 3021 MRP down-regulated the protein expressions of p-IRE1α, BIP and XBP-1 in mouse liver tissues in model group, and inhibited ERS, thereby promoting lipid metabolism and alleviating obesity (Teunis, Nieuwdorp & Hanssen, 2022)." (PMID 37868068, 2023). "Obesity is related to increased iNOS-induced metaflammation and reduced XBP1 processing, similar to study findings in the HFD-induced obesity model." (PMID 35011092, 2022). "The upregulation of XBP1 led to the inhibition of IRE1/IKK/NF-κB pathway which in turn upregulates inflammatory gene expression, leading to adipocyte inflammation and obesity." (PMID 31630283, 2020). "Several of the observed DMCs were located in genes related to T2D or obesity, such as ALOX12, PAMR1, and GNAS in WB; IRS1, LEP, and ADIPOQ in SAT; LCAT, FOXA2, KCNQ1, and GCKR in VAT; and PKD4, HNF4A, XBP1, and PON1 in LT." (PMID 29466957, 2018). "In contrast to the lean phenotype and the resistance to HFD-induced obesity in PIKO mice, inhibition of XBP1 in the hypothalamus results in an obese phenotype in mice, and activation of XBP1 in POMC neurons protects mice against HFD-induced obesity." (PMID 27558934, 2016). "Inhibition of p38 MAPK prevents the nuclear translocation of XBP‐1 without altering total protein levels; however, this mechanism is impaired in obesity." (PMID 41211169, 2025). "In contrast, the incidence of TUNEL-positive cells, although unchanged in β-Xbp1−/−Wt mice, was significantly increased by threefold in β-Xbp1−/−Ob mice, suggesting that the absence of XBP1 increases the rate of beta cell apoptosis under conditions of obesity." (PMID 35316840, 2022). "Xbp1+/− mice exhibit increased ER stress coupled with impaired glucose and insulin tolerance in the high fat diet (HFD)-induced obesity, but in pathological manifestations, activated IRE1α modulates many downstream molecules which consequently result in disease progression." (PMID 32397116, 2020). "Identifying small molecules that enhance XBP1-mediated protective UPR signaling may provide a novel therapeutic strategy against adipocyte inflammation and obesity." (PMID 31630283, 2020). "The lack of effect of TMAO treatment on BW and BMI in HFD-fed mice supports the view that despite Xbp1’s central role in ER stress, adipocyte-specific Xbp1 deletion does not affect obesity." (PMID 28683308, 2017). "XBP1 is known to bind to the promoter region of C/EBPα, which promotes adipogenesis and lipid, and is activated ER stress conditions, such as HFD and obesity." (PMID 28036389, 2016). "Considering the implications of XBP1 and GPR43 in inflammation and obesity, it might be pertinent to further investigate this hypothetical link." (PMID 25633224, 2015). "Importantly, as a novel regulator of metabolic homeostasis, the proposed XBP1 regulation of VEGF also broadens our knowledge on the pathologies of metabolic syndrome and sheds light on the intervention of diabetes mellitus and obesity‐related metabolic diseases." (PMID 27133203, 2016). "Second, we investigated the relationship between XBP1 splicing and CKB expression in white adipose tissue samples from a cohort of people living with and without obesity." (PMID 39675471, 2024).
hepatocellular carcinoma (42 papers, 2012 to 2025). A malignant tumor that arises from hepatocytes. "Another miRNA, miR-214, was recently implicated as a negative regulator of XBP1 expression in hepatocellular carcinomas (HCC)." (PMID 24710528, 2012). "For instance, IRE1α–XBP1 axis promotes angiogenesis and cell proliferation in breast cancers and enhances metabolic inflammation and hepatocyte proliferation in hepatocellular carcinoma." (PMID 40979213, 2025). "The IRE1α‐XBP1 pathway promotes cell proliferation and progression of hepatocellular carcinoma (HCC) with other signalling pathways involved." (PMID 39072992, 2024). "Knockdown of the XBP1 gene by small interfering RNA prevents activation of the SREBP-1c promoter in hepatoma cells, indicating that SREBP-1c is involved in the process of the IRE1α-XBP1 pathway promoting hepatic lipogenesis." (PMID 39770997, 2024). "For example, SPARC, a Ca2+‐binding glycoprotein, which exhibits increased level of expression in hypertrophic scars, has been reported to be upregulated by XBP‐1 in hepatocellular carcinoma cells." (PMID 35435317, 2022). "Three sets of adenoviral shRNAs were generated to deplete the XBP1 gene in Hepatoma 1-6 cells and found that ad-shXBP1-1 and 1-3 had stronger efficacy; therefore, these sets of shRNAs were used in our subsequent studies." (PMID 35863429, 2022). "XBP1 is a key transcription factor of the cellular secretory system, and it is often overexpressed in cancers, such as oral squamous cell carcinoma and hepatocellular carcinoma, and correlates with the clinical outcome." (PMID 34621695, 2021). "New findings suggest that IRE1α-XBP1 signaling promotes development of tumors such as hepatocellular carcinoma (HCC) or melanoma via upregulation of IL-6-driven Janus kinase-signal transducer and activator of transcription 3 (JAK-STAT3) signaling pathway." (PMID 31491919, 2019). "Upregulated XBP1 expression is observed in various human cancers including breast cancer and hepatocellular carcinoma." (PMID 30081573, 2018). "In the present study, several diterpenoids were examined for ability to induce XBP1 splicing and/or lipotoxicity for human hepatoma cell lines." (PMID 26186544, 2015). "MEAO significantly inhibited tunicamycin-induced ER stress marker expression including GRP78, CHOP, and XBP-1 in tunicamycin-treated Human hepatocellular carcinoma (HepG2) cells and the livers of tunicamycin-injected mice." (PMID 26540043, 2015). "A time-dependent induction of XBP1 mRNA splicing also followed treatment with 20 μM GGA in three other human hepatoma cell lines: PLC/PRF/5, HepG-2 and Hep3B." (PMID 26186544, 2015). "Consistently, we found > 50% reduction in Xbp1 transcriptions after 24 h of treatment, demonstrating that miR-214 downregulates Xbp1 in macrophages in addition to cardiomyocytes and hepatocellular cancer cells, implying that Xbp1 negative regulation by exogenous miR-214 is not cell type-restricted." (PMID 39118980, 2024). "Accumulating evidence demonstrated that IRE1α-XBP1 pathway plays a critical role in various cancers, IRE1α-XBP1 pathway was found playing an important role in cell proliferation, tumor progression and invasion in colorectal carcinoma, melanoma, hepatocellular carcinoma and prostate cancer." (PMID 34094948, 2021). "Conversely, miR-214 has been reported to repress Xbp1 expression in hepatocellular carcinoma cells." (PMID 33396504, 2020). "In another study, interaction between IRE1α and RACK1 was crucial for the activation of IRE1α/XBP1 signalling upon unfolded protein response induced by sorafenib in hepatocellular carcinoma cells, further supporting the interconnection between MYC signalling and ER processes." (PMID 32878211, 2020). "Silencing PRKCSH in both hepatoma cell lines decreased the level of spliced XBP1 protein." (PMID 31320625, 2019). "Furthermore, the expression levels of IRE1α–XBP1 target genes were also decreased by PRKCSH silencing in Huh-7 hepatoma cells." (PMID 31320625, 2019).
hepatocellular carcinoma (continued). "XBP1 splicing indicating activation of IRE-1 endonuclease activity was not altered by rhALR upon PA treatment in hepatoma cells and PHH, which underlines that sole cytosolic sfALR reduces PA induced ER-stress pathways." (PMID 28877220, 2017). "Similarly, Huh7 hepatoma cells overexpressing the S protein contained both, the precursor and the spliced form of the Xbp-1 mRNA, suggesting that the envelope protein is also able to trigger UPR via the IRE1/XBP1 pathway." (PMID 25191311, 2014). "For instance, in the case of hepatocellular carcinoma (HCC), IRE1α-XBP1 signaling was found to be important during the initiation of tumor growth, while once the tumor is established, PERK activation is required." (PMID 30754624, 2019). "The exosome miR-21-5p in hepatocellular carcinoma cells can affect hepatocellular carcinoma cell development and patient prognosis by regulating SP1/XBP1 and promoting M2 polarization in TAMs." (PMID 40028181, 2025). "Furthermore, molecular studies demonstrated downregulation of miR-199 in hepatocellular carcinoma (HCC), where it directly suppresses XBP1, providing new insights into HCC pathogenesis." (PMID 39070791, 2024). "In rat liver hepatoma cells, 500-μM PA treatment induced ER stress and elevated PERK and IRE1α phosphorylation, and XBP1 splicing upon PA exposure." (PMID 32542540, 2020). "In human hepatoma cells expressing hepatitis C virus (HCV) sub-genomic replicons, IRE1 is activated as indicated by the enhanced XBP1 S mRNA level, but the transcriptional regulation activity of XBP1 S is inhibited." (PMID 25875739, 2015). "Additionally, activation of the IRE1α‐XBP1 pathway promotes prostate cancer progression via MYC signaling and contributes to hepatocellular carcinoma by enhancing metabolic inflammation." (PMID 40979213, 2025). "In addition, the expression level of XBP-1 mRNA was much higher under hypoxic ICCM treatment than that of normoxia, confirming that hypoxic hepatoma cells are more likely to induce bystander effects." (PMID 27958308, 2016). "No increase in spliced Xbp-1 mRNA was observed in our experiments which is consistent with our previous studies in human hepatoma cells." (PMID 26691022, 2015). "As miR-214 targets XBP-1 and XBP-1 is a key effector of UPR and ER stress, we further investigated whether there might be a link between miR-214 down-expression and the activation of UPR in HCC in hepatoma cells." (PMID 22359598, 2012). "Also, activation of GPR78/BiP, XBP1 and ATF6 were observed in hepatocellular carcinoma cell line compared to non-cancerous liver tissues." (PMID 30081573, 2018).